ZIK1 (zinc finger protein interacting with K protein 1)
Description:
May be a transcriptional repressor.
Synonyms: ZNF762
Tractability: No criterion of Open Targets' tractability assessment is met for any kind of drug.
Gene: Protein-coding gene on chromosome 19 (57,578,456 to 57,593,890, forward strand). Ensembl gene ENSG00000171649.
Subcellular location: Nucleus
Subcellular location (Human Protein Atlas): Intermediate filaments
Pathways (Reactome):
Gene expression (Transcription): Generic Transcription Pathway
Gene Ontology:
Molecular function: protein binding; DNA-binding transcription factor activity, RNA polymerase II-specific; RNA polymerase II cis-regulatory region sequence-specific DNA binding
Biological process: regulation of transcription by RNA polymerase II; regulation of DNA-templated transcription
Cellular component: nucleus
Genetic constraint (gnomAD): Loss-of-function variants: 12 observed, 9.17 expected, observed/expected ratio (o/e) 1.31, 90% interval 0.83 to 1.87. That is too few expected variants to judge how well the gene tolerates losing a copy. Missense variants: 497 observed, 599.53 expected, observed/expected ratio (o/e) 0.83, 90% interval 0.77 to 0.89. Synonymous variants: 190 observed, 205.29 expected, observed/expected ratio (o/e) 0.93, 90% interval 0.82 to 1.04.
Homologues: Orthologues: macaque ZIK1 (97% identical), chimpanzee ZIK1 (97% identical), rabbit ZIK1 (80% identical), mouse Zik1 (70% identical), rat Zik1 (70% identical). Paralogues in human: ZNF551 (54% identical), ZNF256 (53% identical), ZNF792 (52% identical), ZNF304 (49% identical), ZNF549 (47% identical), ZNF548 (46% identical), ZNF587B (46% identical), ZNF418 (44% identical), ZNF772 (40% identical), ZNF583 (39% identical), ZNF419 (39% identical), ZNF773 (39% identical), and 26 more.
Diseases named in the same sentence as ZIK1 in open-access papers:
ZIK1 is named in the same sentence as 5 diseases in open-access papers, as found by Europe PMC text mining. Sharing a sentence is not in itself a finding about the gene and the disease. The quoted sentences say what the papers report.
adenosquamous carcinoma (1 paper, 2023). A carcinoma composed of malignant glandular cells and malignant squamous cells. "These included ZSCAN30 and ZIK1, whose promoters became hypermethylated only in adenosquamous carcinoma." (PMID 37742993, 2023).
ischemic stroke (1 paper, 2025). A stroke disorder caused by obstruction of blood flow to the brain, due to thrombotic (local blood clot formation) or embolic (due to a blood clot or other material traveling from another site) event. "In ischemic stroke, we found that MPO, CALCRL, PPP5C, KTN1-AS1, CCR1, CTB-50L17.9, CCR9, ZNF362, ZIK1, ELP5, CKAP2, NUP88, and SEC16A show risk effects (OR > 1)." (PMID 40624693, 2025).
viral infection (1 paper, 2025). "Notably, the viral infection pathways involved DEGs such as RT1-T24-3 and Zik1, highlighting methamphetamine’s potential role in modulating immune and viral response mechanisms within the brain." (PMID 40003870, 2025).
cancer (3 papers, 2020 to 2023). A tumor composed of atypical neoplastic, often pleomorphic cells that invade other tissues. "Silenced ZIK1 was observed in noncancerous esophageal mucosae, suggesting low expression of ZIK1 occurred at the early stages of cancer." (PMID 36861126, 2023). "From this panel, we have arbitrarily selected 2 representative genes, ZIK1 and ASCL1 (previously identified as being differentially methylated in HPV-associated cancers), for expanded analyses." (PMID 34882728, 2021).
tumor (3 papers, 2021 to 2025). "The expression of ZIK1 was observed to be lower in many of the TCGA tumor types." (PMID 34882728, 2021). "Here, only two fusions were identified as enriched in the tumor cells: the previously identified CBLC::CTC-232P5.1 fusion in 16 cells and our additionally found SNRNP70::ZIK1 in eight cells." (PMID 40086881, 2025). "Here, only 2 fusions identified as enriched in the tumor cells: the previously identified CBLC::CTC-232P5.1 fusion in 16 cells and additionally found SNRNP70::ZIK1 in 8 cells." (PMID 38464114, 2024).